HMOX1 (heme oxygenase 1)
Diseases named in the same sentence as HMOX1 in open-access papers (continued):
Sharing a sentence is not in itself a finding about the gene and the disease.
tumor (continued). "Heme oxygenase-1 (HO-1) and NAD(P)H:oxidoreductase-1 (NQO1) are two representative enzymes, that play key roles in protecting cells and tissues against oxidative stress, inflammation and tumor promotion." (PMID 24489685, 2014). "Our in vivo results identifying FABP4, IL-1β and HMOX-1 as factors influencing invasiveness and tumor growth in the bone but not in the subcutaneous site were recapitulated using bone marrow adipocyte cultures in vitro." (PMID 24240026, 2013). "This study integrated HCC scRNA-seq and RNA-seq data and developed a tumor classification signature (MPCD index) based on extensive bioinformatics analysis and machine learning algorithms, and found four prognostic genes for HCC, S100A9, FYN, LGALS3, and HMOX1." (PMID 39795978, 2024). "In addition, our data showed that pharmacological VC fails to inhibit the ability to form tumor with a rapid growth rate, as well as the phosphorylation of S6K in HMOX1-silenced cells." (PMID 36787291, 2023). "Finally, we discovered that the 12 IMRGs expression had significant differences, among which SFXN3, TFR2, TMPRSS6, HMOX1, and LCN2 expressions were elevated in the cancer group, and SCARA5, LTF, STEAP2, SLC39A14, CP, ALAS2, and TF were low expressed in the tumor group." (PMID 37361050, 2023). "Lipids arising from adipocytes have been demonstrated to increase tumor growth and invasiveness by increasing the expression of fatty acid binding protein 4 (FABP4), a fatty acid chaperone that is involved in glucose and lipid metabolism, heme oxygenase 1 (HMOX), and IL-1β in metastatic tumor cells." (PMID 32092997, 2020). "Delayed tumor growth was dependent upon increased percentages of intra-tumoral cytotoxic CD8+ T cells, with concomitant reductions in regulatory T cells, and elevated expression of the stress-responsive protein heme-oxygenase-1 (HO-1) in the tumor microenvironment." (PMID 31293576, 2019). "The mRNA level of Hmox1 in the tumor tissue of CRC is not correlated with that of the Nrf2 pathway molecules, and its ratio to the Nrf2 level may be useful for suggesting distant metastasis in CRC." (PMID 27999449, 2016). "As cytoplasmic protein HMOX1 is mainly anchored on endoplasmic reticulum, the lack of C-terminal transmembrane segment could induce the translocation of HMOX1 protein to nucleus, which enhances the growth and invasiveness of tumor cells." (PMID 39706989, 2025). "However, unlike Zfp36, HMOX1 has a dual role in tumor cells." (PMID 36835629, 2023). "Furthermore, ferroptosis-related genes with copy number amplification (including FADS2, NQO1, ABCC1, ACSF2, HMOX1, FANCD2 and SQLE) demonstrated higher expression in tumour tissues, and those with copy number deletion (including CRYAB, ACSL3, ZEB1) demonstrated lower expression in tumour tissues." (PMID 35145965, 2022). "Finally, to further examine the clinical significance of HO-1, we used publicly available datasets and found that HO-1 (HMOX1 in the dataset) expression is significantly elevated in GBM tissues compared with non-tumor tissues in all tested datasets (top three panels)." (PMID 28169355, 2017). "Furthermore, we followed by RT-PCR the expression of four selected genes, namely Pten, Hmox1, E2f7 and Nod1 in LLC as well as in other cancer cell lines of human origin, in order to reveal potential common patterns of response to mastic oil among different tumor types." (PMID 20003503, 2009). "TNF-α promotes tumor cell survival and treatment resistance in AML by upregulating heme oxygenase-1 (HO-1) without activating nuclear factor kappa B (NF-KB)." (PMID 35547942, 2022). "Due to poor infiltration of T-cells in these MMTV-PyMT tumors, genetic inactivation of Hmox1 in TAMs neither affected the latency of tumor onset nor the kinetics of tumor growth, however, when 5-FU was administered to elicit a T-cell influx into the TME, tumor control was achieved." (PMID 33868304, 2021).
cancer (679 papers, 2003 to 2026). A tumor composed of atypical neoplastic, often pleomorphic cells that invade other tissues. "It effectively scavenges reactive oxygen species (ROS), which are implicated in aging, cancer, cardiovascular diseases, and neurodegeneration, while simultaneously boosting endogenous antioxidant defenses such as heme oxygenase-1 (HO-1)." (PMID 41254699, 2025). "The HMOX1-ferroptosis axis thus represents both a vulnerability marker and therapeutic lever in inflammation-associated cancers." (PMID 41272089, 2025). "We believe these findings contribute to a deeper understanding of the molecular mechanisms underlying bone pathology associated with cancer metastasis and warrant further investigation into therapeutic strategies targeting the Hif1α/Hmox1 axis." (PMID 39814705, 2025). "And HMOX1 was indicated to be associated with HIF-1a gene related cancer hypoxia and oxygen homeostasis regulation." (PMID 37438709, 2023). "Heme oxygenase 1 (HO-1), the inducible isoform of heme oxygenases, has been implicated in cancer progression as it seems to enhance aggressiveness and resistance to therapies, leading to poor prognosis/outcome." (PMID 35740068, 2022). "The association between HMOX1 promoter polymorphisms and cancer susceptibility has been studied widely, but remains inconsistent." (PMID 33498175, 2021). "Numerous epidemiological studies have shown that an increase in HMOX1 expression is associated with a decrease in the incidence of cancer." (PMID 30057678, 2018). "Hmox-1 gene expression is induced upon expression of oncogenes associated with the induction of some types of cancer." (PMID 27100828, 2016). "Importantly, several key ferroptosis drivers and suppressors, including MAPK1, TLR4, ATM, ULK2, NFS1, and HMOX1, have been identified, offering potential therapeutic targets to modulate cancer cell susceptibility to ferroptosis." (PMID 40868287, 2025). "Additionally, decreased levels of HMOX1, which encodes heme oxygenase 1, also correlates with a less aggressive type of cancer." (PMID 39741355, 2024). "In addition, HMOX1 has been linked to the recurrence of cancer in rats following ischemic liver transplantation and can inhibit the immunomodulatory effect of Treg cells through carbon monoxide produced during metabolism." (PMID 36189226, 2022). "Pan-cancer analysis was first used to identify the metastasis-associated role of HMOX1 in LUAD." (PMID 36033490, 2022). "Polymorphisms in the number of GT repeats in the HMOX1 promoter have also been linked to a susceptibility to cancer, where longer GT repeats, which result in lower basal levels of HO-1 expression, increase the likelihood of the individual developing gastric, lung and oral squamous cancer." (PMID 33868304, 2021). "Studies on the association between the HMOX1 promoter polymorphism and the prevalence of different types of cancer in humans are inconsistent, showing that the same allelic variants seem to be protective against one type of cancer, while posing high risk for other types." (PMID 33498175, 2021). "Then, KLF14 couples with p300 and CREB-binding protein (CBP) to enhance the transcriptional activation of heme oxygenase 1, which encodes the antioxidant enzyme HO-1 that helps cancer cells restore cellular redox balance under androgen-depleted conditions, resulting in cancer cell survival." (PMID 34405016, 2021). "Constitutive NRF2 activation and subsequent deregulation of iron metabolism have been implicated in cancer development: NRF2-mediated upregulation of the iron storage protein ferritin or heme oxygenase 1 can lead to enhanced proliferation and therapy resistance." (PMID 28793787, 2018).
cancer (continued). "Additionally, cancer cells themselves generate mutations that ultimately lead to the expression of genes and increased production of antioxidant enzymes (e.g., heme oxygenase 1, quinine oxidoreductase 1, and NADPH), allowing cancer cells to survive in the mentioned oxidative conditions." (PMID 39885868, 2024). "In addition, the increased level of heme oxygenase 1 (HO-1), which was caused by activation of Nrf2, could prevent anoikis and promote metastasis in carcinoma upon suspension." (PMID 37403143, 2023). "Besides its cardioprotective function, HMOX1 was also demonstrated to have an antitumorigenic role, as shown by Marelli in gut macrophages where HMOX1 expression protects against colitis-associated cancer." (PMID 34836129, 2021). "The compound demonstrates anti-cancer effects primarily by inducing ferroptosis through the overexpression of HMOX1." (PMID 40786960, 2025). "HMOX1, an enzyme that degrades heme to produce free iron, has emerged as a key player in ferroptosis induction across various cancer types." (PMID 40137309, 2025). "Gene expression analysis of PFKFB4 and HMOX1 was performed in all cancer cohorts of TCGA using the TIMER (Tumor Immune Estimation Resource) database." (PMID 40739397, 2025). "Our findings revealed significant differences in gene expression patterns for PFKFB4 and HMOX1 across various cancer types." (PMID 40739397, 2025). "NRF2 overactivation by early growth response 1 (EGR1) leads to increased HMOX1 transcription in breast cancer, providing a survival advantage to the cancer cells and promoting resistance to therapy." (PMID 41333220, 2025). "By utilising the CancerSEA database, we assessed the potential function of SPP1/HMOX1 among pan‐cancer." (PMID 40495644, 2025). "Western blot analysis confirmed that HMOX1 protein levels were successfully reduced after siHMOX1 transfection in both cancer cell lines." (PMID 40790027, 2025). "As mentioned, the antioxidant activity of the heme oxygenase 1 gene (HMOX1) plays a significant role in cancer development by reducing oxidative stress within cancer cells." (PMID 41009002, 2025). "Activation of HMOX1 protects cancer cells against H2O2-induced oxidative stress by upregulating ferritin synthesis and decreasing redox active iron." (PMID 41509286, 2025). "This aligns with other studies suggesting that knocking down PFKFB4 and HMOX1 induces apoptosis and suppresses cancer cell growth." (PMID 40739397, 2025). "The regulation of heme oxygenase-1 (HO-1), also called heat shock protein 32, plays a significant role in cancer therapy due to its role in cellular responses to oxidative stress and inflammation, especially for detoxification and protection." (PMID 39057432, 2024). "According to a recent study, the combination of chemical treatment with an FMD reduces the expression of heme oxygenase-1 (HO-1), which is a stress-responsive enzyme that protects cancer cells against oxidative damage and apoptosis in vivo." (PMID 38462638, 2024). "Several genes relatedto oxidative stress including HMOX1, and the colorectal cancer-relatedgene SEMA4A were upregulated similarly between the enzymatic acroleinproduction system or pure acrolein." (PMID 39155646, 2024). "Subsequently, cell-cell communication analysis indicated that HMOX1+macrophages had the most interactions with cancer cells, while FTH1+macrophages had the fewest." (PMID 39238647, 2024). "Understanding these dynamics is essential for leveraging HMOX1 as a therapeutic target in cancer treatment." (PMID 39534872, 2024). "The iridium (III) complex promotes ROS accumulation in cancer cells to induce ferroptosis by regulating the expression of heme oxygenase 1 (HMOX1)." (PMID 38660623, 2024). "In the process of ferroptosis, HMOX1 was a positive regulator, particularly in certain cancer diseases." (PMID 38245706, 2024). "Secondly, hemoglobin levels are known to increase in cancer, promoting HMOX1 expression in a substrate-dependent manner." (PMID 39850572, 2024).
cancer (continued). "Despite differences in the chemical properties of bortezomib, MG-132, and MLN-2238, treatment with these PIs led to the recurrent dysregulation of 12 genes (e.g. BAG3, DNAJB1, HMOX1) in cell lines representing multiple cancer types." (PMID 39138277, 2024). "Through its antioxidant functions, particularly via bilirubin and carbon monoxide, HMOX1 mitigates oxidative stress and provides a protective advantage to cancer cells, shielding them from ferroptosis." (PMID 39534872, 2024). "Heme oxygenase-1 (HO-1), an inducible enzyme involved in heme catabolism, has emerged as a critical player in cancer biology, including PC." (PMID 39273143, 2024). "It has been demonstrated that curcumin activates Nrf2, improving the effectiveness of cancer treatments by increasing heme oxygenase-1 (HO-1) and decreasing the Nrf2 inhibitor Keap1." (PMID 39456414, 2024). "Hyperoside has demonstrated its efficacy in inhibiting the hypoxia-induced proliferation of cancer cells by enhancing ferrous accumulation in the adenosine monophosphate-activated protein kinase (AMPK)/heme oxygenase-1 (HO-1) axis." (PMID 38915462, 2024). "In particular, we summarize the role of proteins such as nuclear factor-like 2, Sestrin, and heme oxygenase-1, which regulate the expression of various antioxidant genes in metabolic diseases and cancer." (PMID 39309448, 2024). "One of its major targets, heme oxygenase 1 (HO-1), is an antioxidant and detoxifying gene, which can exert either a cytoprotective or detrimental action in cancer, based on the specific cellular conditions." (PMID 38341410, 2024). "Second, oxidized low-density lipoprotein (LDL) in serum not only suppresses T cell function but also upregulates heme oxygenase 1 (HO-1) expression, which induces a cytoprotective stress response to avoid cancer cell apoptosis and leads to ICIs resistance." (PMID 36845142, 2023). "Free heme also induces the accumulation of nuclear heme oxygenase-1, which contributes to the unwinding of the G4 elements and an increase in the genomic instability in cancer cells." (PMID 38201509, 2023). "We found that doxorubicin increased the expression of Hmox1 in wild-type mice, as we previously reported in cancer cells." (PMID 37342339, 2023). "The suppression of NRF2-driven heme oxygenase-1 (HO-1) enhances the chemosensitivity of cancer cells." (PMID 37092860, 2023). "Cancer cell metabolism alterations associate with perturbations of cholesterol synthesis, oxidized low-density-lipoproteins (ox-LDL) through cancer cell expression of the heme oxygenase-1 (HO-1), and sphingolipids diversity and accumulation." (PMID 37180110, 2023). "It has also been reported that targets of the gene Nrf2, including heme oxygenase 1 (HMOX1), initiate the development of cancer as they prevent the oxidative stress effect in cells that are transformed." (PMID 37623253, 2023). "Although its role is not yet fully understood, studies have reported a correlation of HO-1/HMOX1/HSP32 with enhanced cell death in many cancers." (PMID 37559137, 2023). "Suitable levels of HMOX1 in cancer cells have been reported to exert cytoprotective effects via their antioxidant effects." (PMID 36775962, 2023). "Our study provides novel insights into the intricate interplay among macrophage polarization, cucurbitacin I, and heme oxygenase-1, thereby opening new avenues for cancer treatment." (PMID 37958903, 2023). "Increased expression of HMOX-1 in cancer cell lines grown in low [Na+] suggests the role of oxidative stress as the possible molecular basis of hyponatremia-associated poorer outcomes in oncologic patients." (PMID 36831539, 2023). "Heme oxygenase-1 (HO-1) is an enzyme that protects cells (including cancer cells) against oxidative stress, inflammation, and apoptotic effect." (PMID 37894464, 2023).
cancer (continued). "By giving cancerous cells antioxidant and cytoprotective effects and by removing toxic intracellular heme, the inducible intracellular enzyme HMOX1 was also shown to play a role in cancer progression." (PMID 36899871, 2023). "HGF, HMOX1, ELN, and GREM1 genes associate with stromal fibrosis and contribute to malignancy through the proliferation of cancer-associated fibroblasts (CAFs) in various kinds of cancers." (PMID 37240308, 2023). "In this context, several lines of evidence suggest that heme oxygenase-1 (HO-1) and its biological products (CO and biliverdin) represent a possible target for cancer therapy and to overcome chemoresistance." (PMID 36290720, 2022). "Previous studies reported that expression of nuclear factor erythroid 2-related factor 2 (Nrf2) and its regulator, heme oxygenase-1 (HO-1), increased after treating cancer cells with chemotherapeutic agents." (PMID 35715800, 2022). "In conclusion, there is increasing interest in a possible means of inhibiting HMOX-1 expression in order to improve the sensitivity of cancer cells to BRAFV600E inhibitors." (PMID 35053476, 2022). "In all cases, NRF2 activation induces the transcription of antioxidant or antiapoptotic target genes (such as heme oxygenase 1-HO-1) that protect cells from oxidative stress, which is at the basis of many chronic diseases, including cancer." (PMID 35327653, 2022). "In the current study, we demonstrate for the first time that BRAFV600E nuclear localization upregulates 17 cancer-related proteins, with HMOX-1 as the most upregulated." (PMID 35053476, 2022). "Preventing against inflammation-inducing damage and accumulation of ROS, heme oxygenase-1 (HO-1) has a biochemical role in the landscape of lethal illness, such as acute autoimmune response, lung conditions, and malignant tumors." (PMID 36142124, 2022). "CK increases heme oxygenase-1 (HO-1) with anti-inflammatory activity in mice, and exerts anti-cancer effects by promoting caspase-3, which induces apoptosis in vitro and suppresses cell DNA synthesis, inducing cell cycle arrest at the G1 phase." (PMID 36559300, 2022). "Among these candidate molecular targets, nine were significantly enriched in all three cohorts, and five of them (TP53BP1, RIPK2, EHMT2, IGFBP3, and HMOX1) have been reported to have cancer- and chemoresistance-promoting activities simultaneously." (PMID 35606881, 2022). "Although HMOX1 prevents DNA damage under normal conditions, HMOX1 overexpression paradoxically promotes cancer cell proliferation and invasiveness at late phase of tumorigenesis." (PMID 34858984, 2021). "It was shown that overexpression of heme oxygenase-1 (HO-1) promotes proliferation and chemoresistance of cancer cells." (PMID 33498175, 2021). "HMOX1, as the downstream of Nrf2, is involved in the maintenance of cellular homeostasis, but its role in ferroptosis is controversial in cancer cells and renal proximal tubule cells." (PMID 35071238, 2021). "Heme oxygenase-1(HO-1) promotes heme catabolism exercising cytoprotectiveroles in normal and cancer cells." (PMID 34472337, 2021). "Clofibrate, a PPARα agonist, blocks heme oxygenase-1 (HO-1) induction and sensitizes cancer cells to EGCG-promoted cell death." (PMID 34445672, 2021). "Heme oxygenase-1 (HO-1) and sigma receptors (σRs) are both overexpressed in different human cancers, including prostate and brain, contributing to the cancer spreading." (PMID 34202711, 2021). "Among the transcriptional targets of Nrf2, heme-oxygenase 1 (HO-1) not only takes part in heme catabolism but also exerts diversified roles in cancer." (PMID 34360732, 2021). "Studies have found that globular adiponectin (gAcrp) can inhibit the activation of leptin inflammatory bodies through heme oxygenase-1 (HO-1) signaling, thus preventing the cancer-promoting effect of leptin." (PMID 34485124, 2021). "In a nutshell, these findings shed a light on the future for targeting HMOX1 to promote cancer immunotherapy." (PMID 34858984, 2021).